CFTR (CF transmembrane conductance regulator)
Diseases named in the same sentence as CFTR in open-access papers (continued):
Sharing a sentence is not in itself a finding about the gene and the disease.
cystic fibrosis (continued). "In the last decade, molecules that modulate the activity of cystic fibrosis transmembrane conductance regulator (CFTR) mutated proteins (modulators) have significantly improved the morbidity and outcome of patients with cystic fibrosis." (PMID 38259684, 2023). "Cystic fibrosis is a life-shortening genetic disease caused by a mutation in a gene that encodes the cystic fibrosis transmembrane conductance regulator (CFTR)." (PMID 37624013, 2023). "Previously, CFTR has primarily been associated with cystic fibrosis (a recessive disease), but has recently been categorized as a CRC risk gene." (PMID 37296477, 2023). "As for the keyword “cystic fibrosis,” CF is a genetic disorder caused by a defective cystic fibrosis transmembrane conductance regulator (CFTR) gene, which can lead to chronic multisystem disease including severe bronchiectasis." (PMID 36816374, 2023). "In CF, dysfunction of the cystic fibrosis transmembrane conductance regulator (CFTR) causes reduced chloride (Cl−) and bicarbonate (HCO3−) secretion, which adversely affects the biochemical and biophysical properties of mucus, as well as bacterial killing." (PMID 36117114, 2023). "Cystic fibrosis is an autosomal recessive disorder caused by mutations in the gene encoding the Cystic Fibrosis Transmembrane conductance Regulator (CFTR), a chloride/bicarbonate channel that regulates the electrolyte content of luminal fluid." (PMID 38123809, 2023). "Cystic fibrosis is a genetic disorder characterized by mutations in the cystic fibrosis transmembrane regulator (CFTR) and physiologic alterations in the lung." (PMID 37370396, 2023). "Individuals with cystic fibrosis, caused by biallelic germline mutations in the cystic fibrosis transmembrane conductance regulator (CFTR), have higher risk and earlier onset of colorectal cancer (CRC)." (PMID 36765944, 2023). "CF is caused by mutations in the gene encoding the cystic fibrosis transmembrane conductance regulator (CFTR), a chloride and bicarbonate ion transport channel." (PMID 36901843, 2023). "Cystic fibrosis, for example, is a monogenetic disease caused by mutations in the CF transmembrane conductance regulator (CFTR) gene that, consequently, affects the expression of functional CFTR protein, which plays an essential role in homeostasis and regulator processes." (PMID 36896650, 2023). "Cystic fibrosis is a multisystemic autosomal recessive disease caused by a defect in the expression of the CFTR protein, and more than 2000 genetic variants are known." (PMID 38203285, 2023). "CF is a genetic disease caused by mutations in cystic fibrosis transmembrane conductance regulator (CFTR), the cloning of which was performed in 1989." (PMID 37968609, 2023). "Highly effective drugs modulating the defective protein encoded by the CFTR gene have revolutionized cystic fibrosis therapy." (PMID 37024122, 2023). "Cystic Fibrosis is caused by mutations in the CF transmembrane conductance regulator (CFTR), a chloride/bicarbonate channel." (PMID 36674762, 2023). "Cystic fibrosis is a multiorgan disease, caused by autosomal recessive (AR) mutations in the cystic fibrosis transmembrane regulator (CFTR) acting primarily as a chloride channel." (PMID 37842418, 2023). "CF is caused by mutations in the gene encoding the cystic fibrosis transmembrane conductance regulator (CFTR), an anion channel regulated by cyclic AMP-dependent phosphorylation." (PMID 38027060, 2023). "CF is caused by a mutation(s) in the cystic fibrosis transmembrane conductance regulator (CFTR) protein, which results in defects in the expression or activity of a chloride channel located in the cell membrane." (PMID 37373913, 2023). "CF is caused by mutations in a single gene, the Cystic Fibrosis Transmembrane Conductance Regulator (CFTR) gene, which was first described in 1989." (PMID 37250046, 2023).
cystic fibrosis (continued). "CF, a genetic disorder caused by a mutation in the cystic fibrosis transmembrane conductance regulator (CFTR) gene, is characterized by highly viscous mucus in the airways and chronic, polymicrobial respiratory infections." (PMID 36602344, 2023). "Pathogenic CFTR variants cause cystic fibrosis, and CF-related disorders (CF-RD), including bilateral aplasia of the vas deferens (CBAVD)." (PMID 38003474, 2023). "Cystic fibrosis is an autosomal recessive disorder caused by mutations in the cystic fibrosis transmembrane regulator (CFTR) gene that impairs the balance of salts and water across epithelia." (PMID 37293838, 2023). "Mutations of the cystic fibrosis transmembrane conductance regulator (CFTR) gene leading to CF affect the function of several organs and tissues, particularly the bronchial epithelial cells." (PMID 37680748, 2023). "Cystic fibrosis is a life-threatening autosomal recessive multiorgan disorder, caused by mutations in the gene encoding the CF transmembrane conductance regulator (CFTR) that mediates chloride transport through the mucus-producing cells." (PMID 38275311, 2023). "CF is caused by the loss of function of the Cystic Fibrosis Transmembrane Conductance Regulator (CFTR) protein, a member of the ATP-binding cassette family, which functions as a chloride and bicarbonate channel in the apical membrane of multiple epithelia." (PMID 36674762, 2023). "Cystic Fibrosis is caused by mutations in the Cystic Fibrosis Transmembrane conductance Regulator (CFTR) gene, which encodes a chloride and bicarbonate channel widely expressed in human epithelia." (PMID 36627352, 2023). "Cystic fibrosis is an autosomal recessive genetic pathology caused by a mutation in the cystic fibrosis transmembrane conductance regulator (CFTR) gene." (PMID 38298553, 2023). "CFTR functions as a chloride channel in the plasma membrane, and mutations in CFTR cause the disease cystic fibrosis." (PMID 36609925, 2023). "Cystic fibrosis is a congenitaldisorder caused by impaired function of the cystic fibrosis transmembraneconductance regulator (CFTR) protein, whichfunctions as an epithelial anion channel." (PMID 37849531, 2023). "Cystic fibrosis is primarily considered as a lung disease, caused by autosomal recessive mutations in the gene encoding for cystic fibrosis transmembrane conductance regulator (CFTR), a protein channel that controls the flow of H2O and CI- ions in and out of the cells inside the lungs." (PMID 36678793, 2023). "CF is caused by mutations in the gene coding for the cystic fibrosis transmembrane conductance regulator (CFTR) ion channel located at the apical pole of epithelial cells which plays a key role in mucus homeostasis." (PMID 37047579, 2023). "CF is caused by mutations in the gene coding for the cystic fibrosis transmembrane conductance regulator (CFTR): an epithelial ion channel." (PMID 39139270, 2023). "In the CF lungs, mutations in the cystic fibrosis transmembrane conductance regulator (CFTR) gene lead to the production of highly viscous, hyper-concentrated mucus." (PMID 37975659, 2023). "CF is a life-limiting and incurable metabolic disease caused by a gene mutation leading to dysfunction of the ‘cystic fibrosis transmembrane conductance regulator (CFTR) protein’." (PMID 37264349, 2023). "Interestingly, ionocytes have recently been described as a new airway epithelial cell type in humans and mice and it is these cells that most highly express cystic fibrosis transmembrane conductance regulator (CFTR), the anion channel that is mutated in cystic fibrosis patients." (PMID 37078586, 2023). "Cystic fibrosis is a hereditary disorder caused by mutations in the CF transmembrane conductance regulator (CFTR) gene." (PMID 35315363, 2022). "Ivacaftor was the first CF transmembrane conductance regulator (CFTR) modulator therapy to be licensed for the treatment of people with cystic fibrosis with specific CF-causing genetic mutations." (PMID 34497037, 2022).
cystic fibrosis (continued). "In clinical routine, the diagnosis of Cystic Fibrosis is confirmed in the presence of both clinical manifestations of the disease and evidence of CFTR loss-of-function, according to consensus, yet guidelines are still evolving." (PMID 35954202, 2022). "CF is caused by mutations in a single gene encoding a product named cystic fibrosis transmembrane conductance regulator (CFTR)." (PMID 36304167, 2022). "CF is a recessive monogenic disease due to mutations in the Cystic Fibrosis Transmembrane conductance Regulator (CFTR) gene, encoding a chloride channel." (PMID 35784330, 2022). "CF is caused by mutations in the cystic fibrosis transmembrane conductance regulator (CFTR) gene, resulting in dysfunction of the CFTR protein." (PMID 35160099, 2022). "Macrophages represent prominent immune orchestrators of cystic fibrosis inflammation and, as such, are an ever-increasing focus of CF research with several reports of intrinsic immune dysfunction related to loss of CFTR activity in macrophages themselves." (PMID 34799297, 2022). "Cystic fibrosis is an autosomal recessive, multisystemic disorder caused by mutations in the cystic fibrosis transmembrane conductance regulator (CFTR) gene." (PMID 35935370, 2022). "Cystic fibrosis is a monogenic disease caused by a spectrum of mutations in the cystic fibrosis transmembrane conductance regulator (CFTR) gene, which mostly affects the pulmonary and gastrointestinal tract, causing the accumulation of viscous mucous." (PMID 35365227, 2022). "However, this may be due to a high usage of pre-implantation genetic diagnosis (PGD), which is an adjunct technology of ART used to screen out embryos with a mutation, which in this case is the CFTR gene, responsible for cystic fibrosis." (PMID 36013030, 2022). "This is exemplified in the context of pulmonary diseases and cystic fibrosis, a genetic disorder caused by a mutation in the CF transmembrane conductance regulator-encoding gene CFTR." (PMID 35237275, 2022). "However, combined cell and gene therapy using AAVs, lentiviruses or CRISPR-based approaches has also been extensively investigated in the setting of cystic fibrosis, a disease that is caused by mutations in the cystic fibrosis transmembrane conductance regulator (CFTR) gene." (PMID 36239242, 2022). "Microbial antibiotic resistance is relatively common in isolates obtained from people with cystic fibrosis, a disease caused by defective activity or targeting of the cystic fibrosis transmembrane conductance regulator (CFTR)." (PMID 35304578, 2022). "A third study performed at King Faisal Specialist Hospital and Research Center (KFSHRC) in Riyadh showed 396 patients with confirmed CF with positive cystic fibrosis transmembrane conductance regulator (CFTR) variants from January 1992 to December 2017." (PMID 35208595, 2022). "The Cystic Fibrosis Transmembrane Conductance Regulator (CFTR) gene encodes for a chloride channel defective in Cystic Fibrosis." (PMID 36012615, 2022). "Individuals with cystic fibrosis are susceptible to pulmonary infection with Pseudomonas aeruginosa due to defects in the cystic fibrosis transmembrane conductance regulator (CFTR) that result in impaired mucociliary clearance." (PMID 36509824, 2022). "Cystic fibrosis is an inherited, autosomal recessive disorder, caused by pathogenic variants of the CF transmembrane conductance regulator (CFTR) gene." (PMID 36364928, 2022). "Cystic fibrosis is caused by mutations in the gene encoding of the cystic fibrosis transmembrane conductance regulator (CFTR), an anion-selective plasma membrane channel that mainly regulates chloride transport in a variety of epithelia." (PMID 36077010, 2022). "In cystic fibrosis, the absence or functional deficiency of the cystic fibrosis transmembrane conductance regulator (CFTR) protein leads to dysfunctional electrolyte and fluid excretion from cells, resulting in viscous body fluids." (PMID 36466839, 2022).
cystic fibrosis (continued). "One factor that has been suggested to increase the risk of infections in persons with CF is innate immune defects caused by the loss of the cystic fibrosis transmembrane conductance regulator (CFTR−/−)." (PMID 35887506, 2022). "CF is caused by defects in a recessive gene, the cystic fibrosis transmembrane conductance regulator (CFTR)." (PMID 35088244, 2022). "Cystic Fibrosis is an autosomal recessive disease caused by mutations in the gene encoding for the Cystic Fibrosis Transmembrane conductance Regulator (CFTR) protein, expressed on the apical surface of epithelial cells." (PMID 35406809, 2022). "Cystic fibrosis is an autosomal recessive genetic disease caused by variants of the gene encoding the cystic fibrosis transmembrane conductance regulator (CFTR) protein, which affects about 1 of 2700 newborns." (PMID 36015300, 2022). "Genetic variations that impact CFTR function constitute the cause of cystic fibrosis, an autosomal recessive disorder most commonly observed in populations of European descent." (PMID 34652573, 2022). "CFTR gene mutations that result in the introduction of premature termination codons (PTCs) are common in cystic fibrosis." (PMID 35017302, 2022). "Mutations in CFTR that diminish the ion channel function and lead to impaired epithelial fluid transport cause cystic fibrosis, the most common autosomal recessive disorder among European populations." (PMID 36264955, 2022). "Cystic fibrosis is a degenerative multi-system disease caused by pathogenic variants in the cystic fibrosis transmembrane conductance regulator (CFTR) gene." (PMID 35402437, 2022). "In cystic fibrosis patients, the mutation of the CF transmembrane conductance regulator gene leads to an accumulation of dry and sticky airway secretions, creating the perfect environment for the onset of bacterial pulmonary infections." (PMID 35563420, 2022). "Cystic fibrosis is a lethal genetic disorder caused by mutations in the cystic fibrosis transmembrane conductance regulator (CFTR) gene, which encodes a chloride channel protein." (PMID 36505429, 2022). "In addition to vitamin supplementation, cystic fibrosis patients’ vitamin D and E body stores may be affected by pancreatic exocrine function and by mutations in the CFTR gene." (PMID 36364923, 2022). "Cystic fibrosis is one of the major causes of pancreatic lithiasis in pediatric patients, with mutations in the CF transmembrane conductance regulator (CFTR) gene reported in up to 23% of pediatric CP patients." (PMID 37168618, 2022). "Mutations in CFTR are associated with Cystic Fibrosis, the most common lethal autosomal recessive disorder in Caucasians." (PMID 35156780, 2022). "Mutations in CFTR are observed in the vast majority of individuals with cystic fibrosis and are responsible for clinical symptoms, which include respiratory and digestive problems due to the accumulation of thick and sticky mucus." (PMID 35997536, 2022). "Cystic fibrosis is a congenital recessive autosomal disease caused by the transmission of a mutation in the CFTR (Cystic Fibrosis Transmembrane Conductance Regulator) gene." (PMID 36362659, 2022). "In cystic fibrosis, loss of CFTR chloride channel function causes airway surface dehydration, bacterial infection, and inflammation." (PMID 36219481, 2022). "Cystic fibrosis, an autosomal genetic disorder caused by the dysfunction of the cystic fibrosis transmembrane conductance regulator (CFTR) channel, is characterized by failed mucociliary clearance due to abnormal mucus biophysical properties." (PMID 36142171, 2022). "Before the arrival of Cystic Fibrosis Transmembrane Conductance Regulator (CFTR) modulators women with CF and impaired lung function were experiencing a high risk of complications and mortality during and the years after pregnancy." (PMID 36386288, 2022).
cystic fibrosis (continued). "Cystic fibrosis is a severe ion channel disease of autosomal recessive inheritance that is caused by mutations in the cystic fibrosis transmembrane conductance regulator (CFTR) gene." (PMID 36154176, 2022). "Cystic Fibrosis is a chronic, life-limiting illness caused by defects in the cystic fibrosis transmembrane conductance regulator (CFTR) gene." (PMID 35147829, 2022). "CF is caused by mutations in the gene encoding for the cystic fibrosis transmembrane conductance regulator (CFTR) anion channel." (PMID 35328596, 2022). "Loss of CFTR function due to severe pathogenic variants in both alleles of the CFTR gene causes cystic fibrosis." (PMID 35196991, 2022). "The cystic fibrosis transmembrane conductance regulator (CFTR) was first identified by positional cloning in 1989, and its mutation was subsequently associated with CF and CAVD." (PMID 36437957, 2022). "CF is a disease that arises from mutations in the cystic fibrosis transmembrane conductance regulator (CFTR) gene, resulting in disruptions of bicarbonate and salt flux and an accumulation of mucus in exocrine glands." (PMID 35769082, 2022). "This process is affected in cystic fibrosis (CF, 219700), a disease caused by mutations in the gene encoding for the CFTR." (PMID 34671987, 2022). "Cystic fibrosis is a genetic disease that affects the exocrine glands and is caused by cystic fibrosis transmembrane conductance regulator gene (CFTR) mutations." (PMID 36601503, 2022). "A prominent example of this is airway organoids that model cystic fibrosis, a disease caused by mutations of a single gene—the cystic fibrosis transmembrane conductance regulator (CFTR) gene." (PMID 35410254, 2022). "CF is an autosomal recessive disorder caused by mutation of the CYSTIC FIBROSIS TRANSMEMBRANE CONDUCTANCE REGULATOR (CFTR) gene." (PMID 35889173, 2022). "Life expectancy and clinical outcomes for patients with CF have significantly improved with widespread use of highly effective cystic fibrosis transmembrane conductance regulator (CFTR) modulators, including the risk for undernutrition." (PMID 35057491, 2022). "CF is caused by mutations in the cystic fibrosis transmembrane conductance regulator (CFTR) (Ratjen and Döring 2003)." (PMID 34689261, 2022). "MCT is defective in cystic fibrosis, a life-threatening genetic disease caused by mutations in the gene encoding the cystic fibrosis transmembrane conductance regulator (CFTR) anion channel." (PMID 35324331, 2022). "Cystic fibrosis is due to mutations occurring in the CF Transmembrane Conductance Regulator (CFTR) gene, leading to the lack/dysfunction of the CFTR protein at the apical side of absorptive/secretive epithelia." (PMID 35629422, 2022). "Cystic fibrosis is a well-defined genetic disorder caused by biallelic mutations in the CFTR gene with specific diagnostic criteria." (PMID 36046477, 2022). "Cystic fibrosis represents an autosomal recessive multi-systemic disease caused by mutations of the cystic fibrosis transmembrane conductance regulator (CFTR) gene." (PMID 35743234, 2022). "In most cases, CF is caused by the genetic mutation of the cystic fibrosis transmembrane conductance regulator (CFTR) gene." (PMID 35158821, 2022). "Cystic fibrosis is caused by variants in a single gene called the CF transmembrane conductance regulator (CFTR)." (PMID 35637239, 2022). "Cystic fibrosis is caused by mutations in the cystic fibrosis transmembrane regulator (CFTR) gene that encodes a chloride channel." (PMID 36157581, 2022). "Cystic Fibrosis [CF (MIM:219700)] is a common life-limiting autosomal recessive genetic disease caused by pathogenic variants in the cystic fibrosis transmembrane conductance regulator (CFTR; MIM:602421)." (PMID 35396391, 2022). "Cystic fibrosis is caused by mutations of the cystic fibrosis transmembrane conductance regulator (CFTR) gene." (PMID 35887098, 2022).